ATF4 (activating transcription factor 4)
Diseases named in the same sentence as ATF4 in open-access papers (continued):
Sharing a sentence is not in itself a finding about the gene and the disease.
osteosarcoma (14 papers, 2016 to 2025). A usually aggressive malignant bone-forming mesenchymal neoplasm, predominantly affecting adolescents and young adults. "To understand how the loss-of-function of ATF4 contributes to osteosarcoma resistance, we focused on the ATF4-responding proteins screened." (PMID 31534554, 2019). "ATF4 induces the transcription of asparagine synthetase, which catalyzes asparagine biosynthesis, facilitating osteosarcoma progression." (PMID 40588654, 2025). "In recent years, numerous investigations on the involvement of ATF4 in osteosarcoma have been reported." (PMID 36303551, 2022). "The study shows a loss of activating transcription factor 4 (ATF4), which is a downstream effector of pancreatic EIF2-α kinase (PERK) and a key regulator of the cellular stress response in BTZ resistance of osteosarcoma." (PMID 36077137, 2022). "The expression of ATF4 has been previously observed in osteosarcoma treated with BTZ, where it retains an apoptosis-inducing activity." (PMID 31534554, 2019). "Evidence shows ATF4 activation is responsible for proteasome inhibitor bortezomib (BTZ)-induced osteosarcoma (OS) cell death." (PMID 31534554, 2019). "Fluorescence in situ hybridization (FISH) and immunohistochemistry were employed to detect the expression and significance of ATF4 in the specimens from osteosarcoma patients." (PMID 31534554, 2019). "Second, inhibition of ATF4 can induce cancer cell death in some cancer cells such as osteosarcoma, lymphomas and epithel cell derived tumors." (PMID 28881638, 2017). "We showed that ATF4 increases Cbl-c expression at the transcriptional level in osteosarcoma." (PMID 31534554, 2019). "In contrast, the present study revealed a loss of ATF4 in clinical osteosarcoma samples and established BTZ-resistant osteosarcoma sublines, which suggests that osteosarcoma cells attain drug resistance by orchestrating adaptive signalling to prevent ATF4 upregulation." (PMID 31534554, 2019). "Furthermore, up-regulation of ATF4 in osteosarcoma cells accompanies tumor progression and supports metastasis." (PMID 27802179, 2016). "In osteosarcoma, NAT10 enhances mRNA stability of activating transcription factor 4 (ATF4) through ac4C modification." (PMID 40588654, 2025). "In the present study, we analyzed the high-throughput RNA-sequencing data and clinical information of 86 osteosarcoma patients, and identified eight prognosis-related genes, including MAP3K5, G6PD, HMOX1, ATF4, ACADVL, MAPK1, MAPK10, and INS." (PMID 37285835, 2023). "The IHC results illustrated that the expression of AVADVL, ATF4, INS and MAPK10 was higher in osteosarcoma tissues compared to normal tissues." (PMID 37285835, 2023). "In this study, we found significant differences between the prognosis of patients with low and high expression levels of ACADVL, ATF4, HMOX1, INS, and MAPK10, indicating that these genes are potential therapeutic targets of osteosarcoma." (PMID 37285835, 2023). "ATF4 and ACADVL are highly expressed in myeloid cells as well as other cell types, which was suggestive of their roles in osteosarcoma progression." (PMID 37285835, 2023). "In human osteosarcoma, suppression of GRP78 increases ATF4-induced cell death via deubiquitination and stability of CHOP." (PMID 36303551, 2022). "Endoplasmic reticulum (ER) stress markers BiP, CHOP, ATF4 and ATF6 were induced in osteosarcoma cells." (PMID 30250645, 2018). "In this study, we demonstrated that miR-193a-3p and miR-193a-5p suppress the metastasis of human osteosarcoma cells by repressing Rab27B and SRR expression, through suppressing the TGFβ, Myc/Max and ATF2/ATF3/ATF4 signaling pathways." (PMID 26913720, 2016). "Moreover, through endoplasmic reticulum (ER) stress-mediated PERK/eIF2/ATF4/CHOP activation and Wnt/β-catenin signal suppresses the development of human osteosarcoma." (PMID 36303551, 2022). "ATF4 devastates RET by inhibiting nonclassical GRP78 to increase osteosarcoma chemosensitivity to bortezomib." (PMID 36303551, 2022).
osteosarcoma (continued). "Instead of transactivating HSPA5 in OS cells 7, 8, ATF4 negatively regulates GRP78 transcription in BTZ-resistant OS cells, thus reinforcing the therapeutic effect of BTZ by the dual targeting of GRP78 and RET in the context of osteosarcoma chemoresistance." (PMID 31534554, 2019). "The absence of RET upregulates ATF4, which accelerates the turnover of RET proteasomes by over-recruitment of its trans-activated E3 ligase CPL-C, thereby enhancing the chemotherapy effect of BTZ and preventing BTZ resistance in osteosarcoma cells." (PMID 36551309, 2022).
ovarian carcinoma (14 papers, 2019 to 2026). A malignant neoplasm originating from the surface ovarian epithelium. "The genes of the core factor ATF4 of these two pathways are significantly expressed in ovarian cancer tissue and are associated with a poor prognosis." (PMID 39192972, 2024). "Notably, ATF4 was associated with COL1A1 in clinical ovarian cancer tissues from TCGA and GSE156699 datasets." (PMID 40126173, 2025). "Collectively, these results indicate that HF inhibited COL1A1 expression through mTOR‐eIF2α‐ATF4 axis in ovarian cancer CAFs." (PMID 40126173, 2025). "ATF4 expression was associated with chemotherapy response and COL1A1 expression in ovarian cancer by IHC using tissues microarray." (PMID 40126173, 2025). "Bioinformatic analyses indicated that genes encoding core factors of these two pathways, and activating transcription factor 4 (ATF4), were significantly expressed in ovarian cancer tissues and correlated with poor prognosis." (PMID 37215446, 2023). "A significant association between poor overall survival and high CCDC106 and ATF4 expression levels was observed in human ovarian cancer samples." (PMID 35484984, 2022). "In line with this, our study demonstrated that ATF4 is significantly expressed in four ovarian cancer cell lines." (PMID 35484984, 2022). "A previous study verified that ATF4 is highly expressed in rhein derivative 4a treated ovarian cancer cells." (PMID 35484984, 2022). "We confirmed the expression level of ATF4 in all four ovarian cancer cell lines using Western blot analysis." (PMID 35484984, 2022). "In earlier studies, nearly identical concentration of ISRIB reduced the production of ATF4 induced by thapsigargin in ovarian cancer cells and HEK293 cells." (PMID 34445595, 2021). "ATF4 rescued COL1A1 expression under HF treatment in ovarian cancer CAF2." (PMID 40126173, 2025). "The results of multiple gene correlation analyses indicated that there was a significant linear relationship (positive correlation) between the expression of ATF4 in ovarian cancer tissue and the expression levels of GPX4, GSS, KEAP1, NFE2L2, SLC7A11, ATG3, ATG4D, and ATG5." (PMID 37215446, 2023). "Thus, anisomycin may induce ferroptosis in ovarian cancer stem cells by reducing ATF4 to regulate glutathione metabolism." (PMID 39192972, 2024). "As expected, HF remarkably inhibited phosphorylation of mTOR and eIF2α in ovarian cancer CAF1 and CAF2 respectively, which in turn affected ATF4 expression in a time‐dependent manner." (PMID 40126173, 2025).
ovarian carcinoma (continued). "In ovarian cancer, 6‐shogaol increases the concentration of ER stress markers such as GRP78, p‐PERK, p‐eIF2α, ATF4, and CHOP." (PMID 39055196, 2024). "To further investigate SCD1-induced apoptosis in ovarian cancer cells, we analyzed the expression levels of ER stress marker proteins, two master regulators (P-PERK, IRE1α) and their downstream effectors (ATF4 and CHOP)." (PMID 38566208, 2024). "The results of the data analysis indicated that the contents of ATF4, GPX4, GSS, KEAP1, and ATG3 in the peripheral blood exosomes of patients with ovarian cancer were significantly higher than those of the healthy controls." (PMID 37215446, 2023). "6-shogaol induces cell death and ER stress-related markers, such as GRP78, p-PERK, p-eIF2α, ATF4, and CHOP, via the upregulation of Nox4, and ROS and intracellular Ca2+ release in ovarian cancer cells." (PMID 36768961, 2023). "Finally, we explored whether factors such as ATF4, GPX4, GSS, KEAP1, NFE2 like BZIP transcription factor 2 (NEF2L2), SLC7A11, SQSTM1, ATG3, ATG4D, and ATG5 have potential as non-invasive diagnostic markers for ovarian cancer." (PMID 37215446, 2023). "In our study, we demonstrated that knockdown of CREBBP dramatically decreased PERK/ATF4/STC2 expression, and promoted apoptosis in ovarian cancer cells treated with CDDP." (PMID 34149923, 2021). "The Kaplan-Meier plot analysis showed that ATF4 also had a significant negative correlation with the survival of patients with ovarian cancer." (PMID 37215446, 2023). "In addition, we performed exosome database screening and found that the levels of ATF4, GPX4, GSS, KEAP1, and ATG3 in the peripheral blood exosomes of patients with ovarian cancer were significantly higher than those from the healthy controls." (PMID 37215446, 2023). "Finally, analysis using a peripheral blood exosome database indicated that the contents of key factors (e.g., ATF4, GPX4, and ATG3) in peripheral blood exosomes from patients with ovarian cancer, were significantly higher than those of the healthy controls." (PMID 37215446, 2023). "In addition, the overall survival of ovarian cancer patients with high levels of CCDC106 and ATF4 was significantly lower than patients with low levels of CCDC106 (p = 0.0088) and ATF4 (p = 0.0045)." (PMID 35484984, 2022). "Consistent with our previous findings using SpiD7 in ovarian cancer models, SpiD3 treatment activated sustained UPR signaling in CLL cells evidenced by an accumulation of unfolded proteins, PERK activation, and increased expression of ATF4, CHOP, and spliced XBP1." (PMID 38687198, 2024).
cervical carcinoma (13 papers, 2017 to 2024). A carcinoma arising from either the exocervical squamous epithelium or the endocervical glandular epithelium. "Induction of ER-stress in cervical carcinoma cells (HeLa) by glucose deprivation showed early upregulation of ATF4 and other target genes of this stress response pathway such as DDIT3, GADD34, ATF3, and EIF4EBP1 at 24 h." (PMID 33413684, 2021). "Based on our previous study, we also used HeLa cells, a cervical cancer cell line, as a positive control of ATF4 expression under amino acid deprivation." (PMID 28460466, 2017). "In the cervical carcinoma HeLa cells KRT16, FAM129A and HKDC1 transcripts were also induced in response to treatments associated with ATF4 upregulation and in response to ectopic overexpression of ATF4." (PMID 29420561, 2018). "Benzyl isothiocyanate (BITC) blocks the U14 cell cycle and has a role in upregulating ERS IRE1α gene, Atf4 gene, CHOP gene, and protein expression; this suggests that ERS plays an important role in BITC-induced cervical cancer cell apoptosis." (PMID 38711526, 2024). "Bortezomib activates endoplasmic reticulum stress (ERS) in cervical cancer HeLa cells and promotes the expression of GRP78, ATF4 and CCAAT, and it induces autophagy and apoptosis in cervical cancer cells, thereby inhibiting cell proliferation, resulting in anticancer activity." (PMID 37858217, 2023). "Combined protein–protein interaction network, hub gene screening, and qPCR validation data showed that ERs-related genes (ATF4 and DDIT3) and the downstream apoptotic genes (JUN, FOS, BBC3, and PMAIP1) were potential novel targets of 20(S)-GRh2-inducing cervical cancer cell apoptosis." (PMID 36431966, 2022). "Previously, we found that a stress‐responsive transcription factor, known as activating transcription factor 4 (ATF4), enhances JDP2 gene expression in human astrocytoma U373MG and cervical cancer HeLa cells; however, the role of JDP2 in the ATF4‐mediated stress response remained unclear." (PMID 33108704, 2020). "It implies that ERs-related genes (ATF4 and DDIT3) and downstream apoptosis genes (JUN, FOS, BBC3, and PMAIP1) are the potential targets of 20(S)-GRh2 and might be interacting with each other to be involved in the apoptosis induction in cervical cancer cells." (PMID 36431966, 2022).
Parkinson disease (13 papers, 2013 to 2025). A progressive degenerative disorder of the central nervous system characterized by loss of dopamine producing neurons in the substantia nigra and the presence of Lewy bodies in the substantia nigra and locus coeruleus. "In support, the neuroprotective actions of candesartan were reported to involve inhibition of ER stress in a rotenone model of Parkinson's disease in rats, potentially via inhibition of the ATF4-CHOP-Puma pathway." (PMID 33178092, 2020). "In Parkinson's disease, ATF4 has emerged as a key regulator of dopaminergic neuronal death." (PMID 39995125, 2025). "Recent studies further demonstrate the protective role of pharmacological PHD inhibition by reducing ATF4-CHOP-mediated neuronal death and protecting against oxidative damage in models of neurodegeneration including Parkinson’s and Alzheimer’s disease, where neuronal loss is paramount." (PMID 33819286, 2021). "Interestingly, GSEA also indicated LCNM+-enriched expression of genes that are regulated by several TFs—ATF4, EBF3, STAT3, and MEF2D—all of which are protective against Parkinson’s disease, or associated with NM content in dopamine cells of the substantia nigra." (PMID 41278831, 2025). "Adaptaquin (AQ), a hydroxyquinoline-based inhibitor of PHDs, abrogates ATF4-CHOP-dependent neuronal death and improves functional outcomes in mouse models of ICH and Parkinson’s disease." (PMID 33819286, 2021). "Post-mortem studies have identified ATF4 and DDIT3 in dopaminergic neurons of Parkinson’s patients." (PMID 37353587, 2023).
pulmonary fibrosis (13 papers, 2020 to 2025). Chronic progressive interstitial lung disorder characterized by the replacement of the lung tissue by connective tissue, leading to progressive dyspnea, respiratory failure, or right heart failure. "In bleomycin-induced pulmonary fibrosis, the ATF4-responsive lnc949 alleviates fibrotic remodeling by modulating TGF-β/Smad2/3 and JNK pathways, thus reducing Epithelial–Mesenchymal Transition (EMT) and collagen deposition." (PMID 40777108, 2025). "In respiratory system research, bleomycin-induced mouse models of pulmonary fibrosis were used to demonstrate that ATF4-induced lncRNA lnc949 alleviates fibrosis by modulating TGF-β/Smad2/3 signaling." (PMID 40777108, 2025). "In pulmonary fibrosis, lactic acid exacerbates disease progression by activating the ATF4/CHOP axis and Caspase-12, which induces endoplasmic reticulum stress and apoptosis in alveolar epithelial cells." (PMID 41154544, 2025). "In a lung fibrosis model, mice following bleomycin treatment also demonstrated activation of ER stress genes, ATF4 and ATF6, in the distal airway and honeycomb cysts." (PMID 37978501, 2023). "They showed that TRIB3 attenuates lung fibrosis by negatively regulating ATF4 in lung cells and inhibits lung fibroblast activation by regulating ATF4 expression." (PMID 38139251, 2023). "TRIB3 expression negatively regulated ATF4 expression, which promoted fibroblast proliferation, migration, and activation contributing to pulmonary fibrosis." (PMID 36555349, 2022). "In the present study, we demonstrated that TRIB3 contributes to the A549 epithelial cells’ proliferation and migration and repair; TRIB3 attenuates pulmonary fibrosis by interacting with ATF4." (PMID 36555349, 2022). "Here, we investigated whether ER stress contributes to lung fibrosis following MERS-CoV infection by analyzing the levels of ER-stress-associated genes, such as Perk, Atf4, Chop, Atf6, and X-box binding protein 1 (Xbp1) in the lungs of MERS-CoV-infected hDPP4-Tg mice and sham-infected hDPP4-Tg mice." (PMID 33139653, 2020). "TRIB3 attenuated pulmonary fibrosis by negative regulation of ATF4, while TRIB3 expression markedly inhibited ATF4 promoter-driven transcription activity and down-regulated ATF4 expression." (PMID 36555349, 2022). "To investigate the molecular mechanisms of TRIB3 attenuating lung fibrosis, we postulated that TRIB3 plays a momentous role in IPF through regulation of ATF4." (PMID 36555349, 2022).
Cerebral ischemia (11 papers, 2018 to 2025). Restriction of arterial blood supply to the brain associated with insufficient oxygenation to support the metabolic requirements of the tissue. "As reported in previous studies, ATF4 levels are upregulated after cerebral ischemia and reperfusion in rats." (PMID 40933575, 2025). "In cerebral ischemia and reperfusion injury, quercetin suppressed ATF4 and CHOP expression to reduce endoplasmic reticulum stress." (PMID 41245353, 2025). "In some ways, the permanent brain ischemia significantly enhanced the ER stress through PERK/eIF2α/ATF4, ATF6 and IRE-1/NF-κB/JNK/p38 signaling." (PMID 29970982, 2018). "In support of this view, is a study reporting that ATF4 could protect neurons against ER stress-induced cell death by regulating parkin expression in the reperfusion phase after cerebral ischemia." (PMID 31416289, 2019). "Furthermore, Park7 could inhibit ferroptosis in cerebral ischemia-reperfusion injury via the Atf4/Hspa5 pathway." (PMID 39343514, 2024). "Using MCAO and in vitro ischemia models, we showed that LINC00894 stabilized EIF5 to enhance the expression of ATF4, which transcriptionally regulated the expression of FGF21 and ACOD1, thus protecting cells from brain ischemia-induced damage." (PMID 39060766, 2024). "Several molecular events indicating induction of ER stress after global brain ischemia were documented, e.g. post-ischemic phosphorylation of eIF2α, expression of CHOP and ATF4 or splicing of XBP1." (PMID 37452223, 2023). "Finally, ATF4 and CHOP immunoreactivity was documented in the CA1 layer 1 day after global brain ischemia." (PMID 37452223, 2023).